LINC01239 (long independently transcribed non-coding RNA 1239)
Gene: Long non-coding RNA gene on chromosome 9 (22,640,681 to 22,824,213, forward strand). Ensembl gene ENSG00000234840.
Diseases named in the same sentence as LINC01239 in open-access papers:
LINC01239 is named in the same sentence as 6 diseases in open-access papers, as found by Europe PMC text mining. Sharing a sentence is not in itself a finding about the gene and the disease. The quoted sentences say what the papers report.
bipolar disorder (1 paper, 2022). A disorder of the brain that causes unusual shifts in mood, energy, activity levels and the ability to carry out day-to-day tasks. "Consistently, another top locus in the intergenic region at LINC01239/ELAVL2 on 9p21.3 in the present study has also been identified as a genome-wide significant locus for bipolar disorder." (PMID 35286190, 2022). "Among the nine genome-wide significant loci, the identified top regions are pinpointed to previously reported GWAS loci for bipolar disorder (miR-2113/POUSF2 and LINC01239) and schizophrenia loci (ZSWIM6)." (PMID 35286190, 2022).
colorectal adenoma (1 paper, 2023). An adenoma that arises from the colon or rectum. "Additionally, LINC01239 has been reported as linked to colorectal adenomas and certain types of liver cancers." (PMID 37862349, 2023).
esophageal cancer (1 paper, 2022). A primary or metastatic malignant neoplasm involving the esophagus. "Previous studies have shown that MIR31HG presents a carcinogenic phenotype in various solid tumors, such as PDAC, squamous cell carcinoma of the head and neck, and esophageal cancer, while the effects of LINC01239 have rarely been reported." (PMID 35570408, 2022).
LINC01239 also shares sentences with these, for which no sentence is quoted: liver cancer (1 paper); mesothelioma (1); pancreatic cancer (1).